CBX2 (chromobox 2)
Diseases named in the same sentence as CBX2 in open-access papers (continued):
Sharing a sentence is not in itself a finding about the gene and the disease.
tumor (continued). "Apart from CBX2, whose data was missing, all other CBX family proteins were significantly differentially expressed between tumor and normal tissues in HCC patients." (PMID 35677563, 2022). "We observed significant positive correlation between a high CBX1, CBX2, CBX3, CBX5, and CBX8 expression and higher tumor grade in LIHC and UCEC tumors." (PMID 36361869, 2022). "We found that the CBXs relative expression followed a similar trend for both tumor subtypes: CBX3 was the highest among all CBXs, while CBX2 was the lowest." (PMID 36292141, 2022). "The expression of CBX genes differs across solid tumors and for CBX1, CBX2, CBX3, CBX4, CBX5, and CBX8 is predominantly upregulated, while for CBX6 and CBX7 is mostly downregulated in tumor tissues." (PMID 36361869, 2022). "Copy number analysis showed higher amplification frequency of CBX2 gene and almost negligible amplification of CBX7, suggesting oncogenic and tumor‐suppressive roles, respectively." (PMID 33400401, 2021). "Glycolytic metabolites, including glucose-6-phosphate, 3-phosphoglycerate, and fructose-6-phosphate, exhibited upregulated expression in high CBX2 and low CBX7 tumor samples." (PMID 34572770, 2021). "By contrast, increased CBX2 and decreased CBX7 in tumor cells result in augmented glycolysis, which in turn supports tumor cell proliferation." (PMID 33400401, 2021). "With regard to regulation of gene expression, DNA methylation of levels CBX2/7 gene inversely and significantly correlated with CBX2 and CBX7 mRNA in tumor samples, suggesting the role of CpG methylation in regulation of their gene expression." (PMID 33400401, 2021). "In order to correlate the CBX2 in vitro findings to clinically relevant specimens, we utilized a tissue microarray (TMA) of HGSOC that recapitulated tumor progression." (PMID 30478317, 2018). "In a correlation analysis between protein expression patterns and established clinicopathological features, a clear link was found between CBX2-positivity and tumor inflammatory infiltration as well as STK32B-positivity and small tumor size (T1-T2)." (PMID 24885002, 2014). "Along with an increase in CBX2 and CEP55, the stepwise stage and tumor grade also increased." (PMID 37980163, 2023). "Additionally, CBX2 and CEP55 had a significantly greater impact on tumor patient survival than PDCD1 and CD274." (PMID 37980163, 2023). "Similarly, mRNA expressions of CBX1, CBX2, CBX3, CBX4, and CBX8 were significantly related to patients’ tumor nodal metastasis status." (PMID 35464847, 2022). "Notably, CBX2 had a lower mRNA expression level in tumor grade IV compared to tumor grade III, and the highest mRNA levels of CBX2 were exhibited in tumor grade III." (PMID 35210369, 2022). "The mRNA levels of CBX2/3/6/7/8 were related to tumor grades, but the mRNA expressions of CBX1/4/5 were not markedly different." (PMID 35210369, 2022). "In our study, we found that CBX2 was not related to the expression, tumor characteristics, or prognosis of ccRCC, which is consistent with the results of previous research." (PMID 34395271, 2021). "Of further interest, we found a KEOPS complex member (gm6890), implicated in homologous double-strand break repair and telomere maintenance, to be strongly upregulated during tumor formation, as well as the checkpoint adaptor Claspin (CLSPN) and three chromosome 17q loci CBX2, GJC1 and LIMD2." (PMID 34638267, 2021). "A significant reduction in 5-year survival in tumours that overexpressed CBX2 vs. those that did not was observed (q = 0.03, log-rank test)." (PMID 30820027, 2019). "Notably, CBX2 and EZH2 were consistently the most highly overexpressed epigenetic regulators across multiple datasets from clinical and xenograft tumor tissues." (PMID 25859291, 2015). "To determine whether CBX2 plays a role in HGSOC tumor cell’s ability to survive without anchorage, or in a suspended setting, we examined the role of CBX2 on HGSOC growth in suspension." (PMID 30478317, 2018).
tumor (continued). "Among the 40 patients with incomplete resection of tumours, the IRS values of 24 patients with a negative TMZ reaction (SD/PD) were higher than those of 16 patients with a positive reaction (CR/PR) (p < 0.001), which indicated that high expression of CBX2 is associated with TMZ chemoresistance." (PMID 39114365, 2024). "This suggests that the downregulation of FOXO3 independent of CBX2 could drive tumor progression." (PMID 30478317, 2018). "Having validated our positive and negative controls for each subtype, we analyzed CBX2 and EZH2 protein levels in both tumor lines." (PMID 25859291, 2015).
hematological malignancies (1 paper, 2018). "Collectively, these findings reveal a potential role for CBX2 in sustaining tumorigenic properties of leukemic cells, highlighting its possible oncogenic role in hematological malignancies." (PMID 29467492, 2018). "In agreement, CBX2 is potentially a tumorigenic target in hematological malignancies, since it regulates stemness and self-renewal of leukemic cells." (PMID 29467492, 2018).
infection (1 paper, 2019). The state of being infected such as from the introduction of a foreign agent such as serum, vaccine, antigenic substance or organism. "The pathways were not significantly impacted by Cbx2-knockdown after infection with either VSV or HSV." (PMID 30357595, 2019).
Reproductive System Disease (1 paper, 2016). "Moreover, other diseases most associated with CRGs included “Developmental Disorder” and “Reproductive System Disease,” both of which have previously been linked to CBX2 mutations in the medical literature." (PMID 26877821, 2016).
CBX2 also shares sentences with these, for which no sentence is quoted: invasive breast carcinoma (2 papers); lymphoma (2); metastatic prostate carcinoma (2); atherosclerosis (1); bacterial infections (1); bladder cancer (1); brain tumor (1); colon cancer (1); endometrial ovarian cancer (1); melanoma (1); pancreatic adenocarcinoma (1); pancreatic cancer (1); polycystic ovary syndrome (1); rectal cancer (1); soft tissue sarcoma (1); squamous cell carcinoma (1).